Y_RNA (Y RNA )
Gene: Miscellaneous RNA gene on chromosome 5 (79,562,745 to 79,562,846, reverse strand). Ensembl gene ENSG00000277818.
Homologues: Paralogues in human: Y_RNA (85% identical), Y_RNA (84% identical), RNY3 (83% identical), RNY3P1 (83% identical), Y_RNA (83% identical), Y_RNA (82% identical), Y_RNA (81% identical), Y_RNA (80% identical), RNY3P11 (79% identical), RNY3P14 (79% identical), RNY3P16 (79% identical), Y_RNA (79% identical), and 94 more.